AMH (anti-Mullerian hormone)
Diseases named in the same sentence as AMH in open-access papers (continued):
Sharing a sentence is not in itself a finding about the gene and the disease.
Infertility (continued). "Although a few studies regarding infertility have been conducted among Bangladeshi people, not much work has been directed at accessing ovarian reserve and its two determining factors: AFC and AMH." (PMID 38077683, 2023). "Multivariable logistic analysis demonstrated that race was an independent predictor of live birth independent of age, parity, BMI, etiology of infertility, ovarian reserve (Day 3 FSH, AMH), cycle cancellation, past spontaneous abortions, use of ICSI or number of embryos transferred." (PMID 33213467, 2020). "The female age, female BMI, pregnancy history (gravida, para, abortion), female AMH levels, previous IVF cycles, duration of infertility, male age, male BMI, and basic semen analysis data were not significantly different between pregnant (n = 26) and nonpregnant (n = 37) couples." (PMID 32724600, 2020). "Basic demographic characteristics, such as age, BMI, age of menarche, duration of infertility, abortion number, infertility aetiology, basic hormone levels (FSH, LH, E2, T, P, AMH, INHB, and DHEAs) and AFC, were not significantly different (P >0.05) between the DHEA and control groups." (PMID 28472976, 2017). "The contrasting observation that AMH levels are not diminished in women with endometriosis, including those with presence of uni- or bilateral OMAs unless they had had previous OMA surgery, was based on data from women undergoing surgery without information on infertility, thus biasing the results." (PMID 34405378, 2022).
polycystic ovary syndrome (179 papers, 2010 to 2026). A disorder that manifests as multiple cysts on the ovaries. "The latest guidelines emphasize the growing role of AMH in the diagnosis of polycystic ovary syndrome and suggest that it should become one of the diagnostic criteria for identifying this condition." (PMID 40283506, 2025). "The diagnosis of PCOS should be made in the presence of two of clinical or biochemical hyperandrogenism, ovulatory dysfunction and polycystic ovaries on ultrasound or elevated anti-mullerian hormone (AMH) levels, after excluding other potential causes." (PMID 39408349, 2024). "Anti-Müllerian hormone (AMH) levels are increased in polycystic ovary syndrome (PCOS) patients and are associated with PCOS severity." (PMID 37872575, 2023). "In women, AMH can be used as a diagnostic and prognostic marker for ovarian reserve, polycystic ovary syndrome (PCOS), implantation potential, primary ovarian insufficiency (POI), and granulosa cell tumors." (PMID 35565634, 2022). "In the present study, several cardiovascular risk factors and hormonal parameters were found to be significantly associated with CIMT, i.e. visceral obesity, dyslipidemia, hyperandrogenemia, AMH, smoking, SBP and parental history of metabolic disorders." (PMID 32330202, 2020). "The positive relationship of CIMT found with AMH further underlines the impact of hyperandrogenemia." (PMID 32330202, 2020). "BACKGROUND: This study aimed to establish the diagnostic cut-off value of serum Anti-Müllerian Hormone (AMH) for Polycystic Ovary Syndrome (PCOS) in Chinese women of reproductive age and explore its diagnostic efficacy, particularly in relation to age, body mass index, and PCOS phenotypes." (PMID 41545945, 2026). "As an auxiliary diagnostic indicator of PCOS, AMH is associated with hyperandrogenemia and IR." (PMID 37388214, 2023). "Therefore, AMH is increased in patients who suffer from polycystic ovary syndrome (PCOS) and is positively associated with serum levels of testosterone, androstendione, and dehydroepiandrosterone sulfate (DHEAS)." (PMID 32326591, 2020). "Based on the actual PCOS and/or polycystic ovaries diagnostic guidelines and given that women with polycystic ovaries also may have high AMH levels, the diagnostic AMH cut-off value(s) may depend on the age and phenotype as a worsening variable that complicates the detection of polycystic ovaries." (PMID 36672987, 2023). "Additionally, hyperandrogenemia accompanied with higher AMH is associated with decreased oocyte developmental competence, which may also explain the similar pregnancy outcomes of PCOS patients between high-AMH group and other groups." (PMID 35236324, 2022). "While explanations are speculative, it is possible that elevated values of AMH correspond with other disorders, such as polycystic ovary syndrome, which increase the risk of CVD, and women with low values of AMH have minimal ovarian reserve, which may also increase the risk of CVD." (PMID 30766706, 2017). "In contrast, polycystic ovary syndrome (PCOS) is associated with abnormally increased follicular numbers and relatively high serum AMH." (PMID 22136508, 2011). "Increased LH and AMH levels (varying up to 50 ng/mL by unspecified analyses) as well as ultrasound evidence for polycystic ovaries were found by secondary care evaluation, and therapy with oral contraceptives was started." (PMID 41515619, 2026). "Polycystic Ovary Syndrome (PCOS) is the most common endocrine disorder inwomen of reproductive age, being one of the main causes of infertility.Anti-Müllerian hormone (AMH) is an important marker of ovarianreserve and has been proposed as an alternative criterion for the diagnosisof PCOS." (PMID 39983029, 2025). "Samples of all patients were also assayed by LC–MS/MS for hyperandrogenemia and for circulating AMH." (PMID 38913250, 2025). "The mean and median AMH levels for women with polycystic ovary syndrome in the Polish population were estimated." (PMID 40283506, 2025).
polycystic ovary syndrome (continued). "We observed that the mean and median AMH concentrations in women with polycystic ovary syndrome are almost twice as high as those achieved by women in the control group." (PMID 40283506, 2025). "In this context, it has been noted that Cd exposure to female rats resulted in polycystic ovarian syndrome and premature ovarian failure through decreasing AMH levels." (PMID 40360878, 2025). "Serum AMH levels can assist in the diagnosis of polycystic ovaries when an ultrasound examination of the ovaries is complex due to obesity or in poor echogenic patients." (PMID 39634976, 2024). "It is therefore possible that an increased AMH contributes to maternal hyperandrogenemia via GnRH/LH activation." (PMID 38397936, 2024). "Epidemiological studies regarding the correlation between anti-Müllerian hormone (AMH) and insulin resistance (IR) in polycystic ovarian syndrome (PCOS) remain inconsistent." (PMID 38762718, 2024). "There are limited studies directly investigating the relationship between AMH levels and MetS and its components in the general population; most research has focused on women with polycystic ovary syndrome (PCOS)." (PMID 38926704, 2024). "Numerous epidemiological studies indicate that women with polycystic ovarian syndrome (PCOS) exhibit higher serum AMH levels and a relatively increased incidence of EPLs." (PMID 39767233, 2024). "This study aimed to evaluate the cut-off value of anti-Müllerian hormone (AMH) combined with body mass index (BMI) in the diagnosis of polycystic ovary syndrome (PCOS) and polycystic ovary morphology (PCOM)." (PMID 36726106, 2023). "Second, based on the racial diversity of serum AMH, our study was the first to combine anti-Müllerian hormone and BMI to diagnose polycystic ovary syndrome and polycystic ovary morphology in Chinese women." (PMID 36726106, 2023). "Recently, rare heterozygous AMH protein-altering variants were identified in women with polycystic ovary syndrome (PCOS), causing reduced anti-Müllerian hormone (AMH) signaling." (PMID 37004205, 2023). "Women with polycystic ovary syndrome (PCOS) tend to have elevated anti-Müllerian hormone (AMH) levels, which appear to correlate with disease severity and pregnancy outcomes." (PMID 38137371, 2023). "In adolescent females, AMH research primarily focuses on polycystic ovarian syndrome (PCOS), where findings suggest that AMH levels are elevated in adolescents with PCOS 10-12." (PMID 37841846, 2023). "This study aimed to investigate the association between AMH levels and the outcomes of in vitro fertilization (IVF) in patients with polycystic ovary syndrome (PCOS)." (PMID 37388214, 2023). "The anti-Müllerian hormone (AMH) is gaining attention as a key factor in determining ovarian reserve and polycystic ovarian syndrome, and its clinical applications are becoming more widespread worldwide." (PMID 37304879, 2023). "In women with lean PCOS, a significantrelationship was demonstrated with hyperandrogenemia and high AMH levels duringpregnancy." (PMID 37417851, 2023). "Overall, women in the AMH > 5.71 ng/mL group had significantly greater rate of hyperandrogenemia as compared with low-AMH and average-AMH groups (14.3% vs. 7.8% and 8.5%, respectively; P < 0.001)." (PMID 35236324, 2022). "In the PCOS patients with hyperandrogenemia (HA), the AMH level was significantly higher in the subjects with T increased than in the subjects with non-T androgen(s) increased (A2, DHT, DHEA or DHEAS)." (PMID 35757414, 2022). "Previous studies have shown that women with polycystic ovary syndrome have a 2 to 3 times increase in their serum AMH, followed by a 2 to 3 times increase in the number of small follicles (2–5 mm)." (PMID 36042475, 2022). "On the other hand, the stimulating effect of FSH on AMH expression in normal and polycystic ovaries has been described." (PMID 36569727, 2022).
polycystic ovary syndrome (continued). "This article reviews the main findings on anti-Müllerian hormone (AMH) and its involvement in the pathogenesis of polycystic ovary syndrome (PCOS) and its male equivalent." (PMID 36289767, 2022). "Our study was done in women with a normal ovarian function to exclude the influence of elevated AMH serum concentrations, as seen in polycystic ovary syndrome." (PMID 34369004, 2021). "AMH is also now used to predict proximity to menopause and potentially provides a sensitive and specific test for polycystic ovarian syndrome." (PMID 34108942, 2021). "There is emerging evidence that, with improved standardisation of assays and established cut-off levels based on large populations of different ages and ethnicities, AMH assays will become more accurate in the detection of polycystic ovary morphology." (PMID 32204714, 2020). "Circulating insulin levels in patients with PCOS increase, thereby inducing follicular developmental disorders, which in turn lead to ovarian polycystic ovary formation and higher than normal AMH." (PMID 32785222, 2020). "To date, AMH is best known as a serum marker for ovarian function, with assessment of AMH levels at both ends of the spectrum, that is, ovarian reserve and polycystic ovarian syndrome." (PMID 32770239, 2020). "High anti-Müllerian hormone (AMH) levels and 25-hydroxyvitamin D [25(OH)D] deficiency have been associated with polycystic ovarian syndrome (PCOS) in adult women, and implicated in its pathogenesis." (PMID 33218348, 2020). "This elevated serum AMH level was initially considered a reflection of the increased stock of pre-antral and small antral follicles within polycystic ovaries (PCO)." (PMID 33013710, 2020). "Phenotype 1 (anovulation, hyperandrogenism, and polycystic ovaries) shows the highest levels of AMH and HOMA-IR, which decreases in accordance to severity level (p < 0.005)." (PMID 29426356, 2018). "AMH production by granulosa cells in the polycystic ovary is 75 times higher compared to healthy women." (PMID 25119192, 2014). "AMH levels in follicular fluid, selected from follicles 4–8 mm in diameter, were significantly higher in women with anovulatory polycystic ovary syndrome (PCOS) (median 466.2 ng/ml) compared with normal-ovulatory controls (median 78.0 ng/ml)." (PMID 24932501, 2014). "Increased AMH levels have been recommended as a criterion for polycystic ovary syndrome (PCOS)." (PMID 41515619, 2026). "Moreover, their insulin sensitivity index was lower, and their triglyceride concentrations and serum AMH concentrations were higher, than the subgroup of women showing hyperandrogenemia only by immunoassays." (PMID 38913250, 2025). "Additional research indicates that elevated levels of AMH may inhibit follicular development, particularly in women diagnosed with polycystic ovarian syndrome (PCOS)." (PMID 40724853, 2025). "Therefore, we decided to specify the AMH values for women with polycystic ovary syndrome in the Central European population across different age groups." (PMID 40283506, 2025). "The amended Rotterdam consensus has PCOS with evidence-based criteria of at least two of the following needs: (a) clinical or biochemical hyperandrogenism, (b) ovulatory dysfunction, and (c) polycystic ovary morphology (PCOM) or high anti-Mullerian hormone (AMH)." (PMID 41556019, 2025). "Also, another possible mechanism behind LOD's success is the supposed reduction in anti-Mullerian hormone (AMH) concentrations and disruption of the polycystic ovary walls." (PMID 38989366, 2024). "This study aims to determine whether thyroid autoimmunity, age, body mass index (BMI), sexual hormone levels, and 25-hydroxyvitamin D levels influence serum AMH in non-polycystic-ovary-syndrome (PCOS) euthyroid women." (PMID 39336427, 2024). "In addition to being an ovarian reserve marker, AMH plays a potential role in the pathophysiology diagnosis and treatment of several ovarian pathologies, including polycystic ovary syndrome (PCOS)." (PMID 38549135, 2024).
polycystic ovary syndrome (continued). "According to the latest diagnostic criteria, PCOS can be diagnosed by meeting any two of the following criteria: clinical/biochemical hyperandrogenemia, ovulation disorders, and ultrasound evidence of polycystic ovarian manifestations/abnormal Anti-Mullerian Hormone (AMH) levels." (PMID 39911236, 2024). "Based on the best available evidence, it is recommended to diagnose PCOS when at least two of the following exist: clinical or biochemical hyperandrogenism, ovulatory dysfunction, polycystic ovaries on ultrasound, or a high level of anti-Mullerian hormone (AMH)." (PMID 38170129, 2024). "Furthermore, higher serum AMH levels are correlated with ovulation disturbance and hyperandrogenemia, indicating the potential involvement of AMH in the disturbance of follicle formation in PCOS." (PMID 38600539, 2024). "The overproduction of AMH through the accumulation of preantral follicles is attributable to impaired folliculogenesis, hyperandrogenemia and insulin resistance in PCOS, and there is evidence that excess AMH may be associated with the severity of the syndrome." (PMID 38813505, 2023). "Compared with the control group, the maternal age, blood glucose, and baseline FSH (follicle-stimulating hormone) were higher in the Aspirin group, and the endometrial thickness, baseline AMH level, and polycystic ovary syndrome (PCOS) ratio were lower in the Aspirin group." (PMID 36769712, 2023). "Elevated maternal circulating levels of AMH from polycystic ovaries may enhance maternal hyperandrogenism and amplify epigenetic transgenerational transmission of hyperandrogenic and metabolic phenotypes in female offspring through altered placental function." (PMID 37834765, 2023). "In polycystic ovary syndrome (PCOS) the level of AMH is higher." (PMID 37706124, 2023). "Increasing the concentration of AMH affects the pathogenesis of polycystic ovary syndrome." (PMID 36042475, 2022). "In the past decade, apart from insulin resistance and hyperandrogenemia, anti-mullerian hormone (AMH), an important marker of ovarian reserve, and vascular endothelial growth factor (VEGF), a crucial factor in angiogenesis, have been examined as plausible players of causative relevance for PCOS." (PMID 34063169, 2021). "Indeed, AMH levels are increased in women with polycystic ovary syndrome (PCOS); however, this question, with particular reference to anestrus and repeat breeding, has not yet been studied in farm animals." (PMID 33763463, 2021). "In addition, prior studies showed a positive correlation between AMH levels and degree of hyperandrogenemia." (PMID 32156287, 2020). "All patients had polycystic ovaries on ultrasound and therefore it might have expected all of the AMH values to be elevated." (PMID 29491484, 2018). "Mean Anti-Mullerian Hormone / antral follicle count ratio in women with polycystic ovary syndrome or polycystic ovarian morphology was similar to that of the controls (polycystic ovary syndrome: 1,2 p = 0,10 polycystic ovarian morphology: 1,2, p = 0,27 Controls 1,3)." (PMID 26799212, 2016). "The strong correlation of AMH with the number of growing follicles is supported by the fact that its levels are reported very high in ovarian tumors and in polycystic ovaries while undetectable levels are testified in postmenopausal women and Turner syndrome patients without gonadal tissue." (PMID 26977116, 2016). "Young PCOS patients presented with a typical pattern of significant hyperandrogenemia and elevated AMH in comparison to young women with normal functional ovarian reserve [TT 44.0 (32.9–58.7) vs. 23.9 (20.3–28.1) ng/dL, (P<0.05); and AMH 7.7 (6.2–9.1) vs. 2.5 (2.0–3.0) ng/mL, (P<0.05)]." (PMID 26156856, 2015). "A lack of follicular growth may partly explain by increased production of inhibin B and high AMH levels from the increased number of antral follicles in polycystic ovaries." (PMID 26220826, 2015).